CSAG3 (CSAG family member 3)
Description:
Drug-resistance related protein, its expression is associated with the chemotherapy resistant and neoplastic phenotype. May also be linked to the malignant phenotype.
Synonyms: CT24.2; CSAG3A
Tractability: No criterion of Open Targets' tractability assessment is met for any kind of drug.
Gene: Protein-coding gene on chromosome X (152,753,921 to 152,760,222, forward strand). Ensembl gene ENSG00000268916.
Gene Ontology:
Molecular function: protein binding
Biological process: response to xenobiotic stimulus
Homologues: Paralogues in human: CSAG2 (99% identical), CSAG1 (51% identical).
Diseases named in the same sentence as CSAG3 in open-access papers:
CSAG3 is named in the same sentence as 6 diseases in open-access papers, as found by Europe PMC text mining. Sharing a sentence is not in itself a finding about the gene and the disease. The quoted sentences say what the papers report.
chondrosarcoma (1 paper, 2021). A malignant cartilaginous matrix-producing mesenchymal neoplasm arising from the bone and soft tissue. "The other transcript, CSAG3-202 is a non-coding version of the canonical CSAG3 (chondrosarcoma-associated gene) transcript." (PMID 34316711, 2021).
gastric cancer (1 paper, 2019). A primary or metastatic malignant neoplasm involving the stomach. "CSAG3, also known as TRAG-3 (taxol resistance associated gene-3), was reported to be up-regulated in many tumors including gastric cancer, urothelial carcinoma of the bladder, ovarian carcinoma, and melanoma." (PMID 30755830, 2019).
hepatocellular carcinoma (1 paper, 2021). A malignant tumor that arises from hepatocytes. "CSAG1 and CSAG3 were representative factors for the alcohol-induced hepatocellular carcinoma, which implies that the results of the present study using capillaries were consistent with the in vivo findings." (PMID 34066517, 2021).
cancer (2 papers, 2018 to 2019). A tumor composed of atypical neoplastic, often pleomorphic cells that invade other tissues. "Examples of biclusters from this category include the biclusters consisting of genes from the Cancer-Testis antigens family—MAGEA2, MAGEA3, MAGEA6, MAGEA10, CSAG1, CSAG2, CSAG3 (Xq28)/CT45A3, CT45A5, CT45A6 (Xq26.3)." (PMID 31216036, 2019).
CSAG3 also shares sentences with these, for which no sentence is quoted: tumor (1 paper); urothelial carcinoma of the bladder (1).